PSMD10P1 (proteasome 26S subunit, non-ATPase, 10 pseudogene 1)
Synonyms: dJ914P20.4; formerly PSMD10P
Gene: Processed pseudogene on chromosome 20 (50,913,731 to 50,914,411, forward strand). Ensembl gene ENSG00000228663.
Diseases named in the same sentence as PSMD10P1 in open-access papers:
PSMD10P1 is named in the same sentence as 1 disease in open-access papers, as found by Europe PMC text mining. Sharing a sentence is not in itself a finding about the gene and the disease. The quoted sentences say what the papers report.
lung adenocarcinoma (1 paper, 2023). A carcinoma that arises from the lung and is characterized by the presence of malignant glandular epithelial cells. "Zhang and collaborators (2021) have identified seven N6-methyladenosine-related immune prognostic genes (i.e., PSMD10P1, DIDO1, ABCA5, CIITA, PRC1, ZWILCH, and ANLN) for lung adenocarcinoma (LUAD)." (PMID 37189849, 2023).